BRCA2 (BRCA2 DNA repair associated)
Diseases named in the same sentence as BRCA2 in open-access papers (continued):
Sharing a sentence is not in itself a finding about the gene and the disease.
breast cancer (continued). "TLK2 is amplified/upregulated in 26 % of sporadic breast cancer cases, and its amplification/upregulation is mutually exclusive to BRCA2 deletion/downregulation." (PMID 26427375, 2015). "The efficacy of the software is verified through MDS and clustering and tested with available 11 familial non-BRCA1/BRCA2 breast cancer exome data." (PMID 25905921, 2015). "We first tested the expression levels of canine BRCA2 in mammary gland and mammary tumor samples by qRT-PCR." (PMID 26202431, 2015). "With the availability of a three-tube multiplex for the complete BRCA1 and BRCA2 genes we sought to apply this approach to a cohort of Hispanic/Latin American breast cancer patients." (PMID 26543556, 2015). "The major breast cancer susceptibility genes, BRCA1 and BRCA2, play a role in the homologous recombination pathway (HR) for repairing the double strand breaks (DSB) in DNA3." (PMID 26108708, 2015). "As with BRCA2, germ line mutations of PALB2 confer increased risk of breast cancer as well as ovarian and pancreatic cancer." (PMID 26082817, 2015). "AZD2281 induced significant autophagy (37 and 44%) in BRCA1 mutant SUM-149PT and BRCA2 mutant HCC-1428 breast cancer breast cancers, respectively, in 24 of treatment." (PMID 25975349, 2015). "PARP inhibitors are considered promising anti-cancer agents and currently being tested in clinical trials in hereditary breast cancer patients harboring mutations in BRCA1 and BRCA2 genes." (PMID 25975349, 2015). "In this study, we showed that canine BRCA2 mRNA transcript levels were significantly reduced in mammary tumor samples compared to normal mammary gland tissue." (PMID 26202431, 2015). "Mutations confer a high risk of breast and ovarian cancer with estimated breast cancer penetrances of 60% for BRCA1 and 55% for BRCA2 by age 70 years." (PMID 25848941, 2015). "We observed the same phenomenon by AZD2281 in BRCA wild-type breast cancer cell line MDA-MB-231 with BRCA1 or BRCA2 downregulation." (PMID 25975349, 2015). "Major advances in the understanding of breast cancer susceptibility were made in the 1990s when the two major high-risk breast cancer and ovarian cancer predisposition genes BRCA1 and BRCA2 were identified." (PMID 26082817, 2015). "To this end we treated BRCA1 mutant (SUM-149PT) and BRCA2 mutant (HCC-1428) breast cancer cells with 2 μM AZD2281 for 1 day and stained them with acridine orange." (PMID 25975349, 2015). "Reduced expression of canine BRCA2 mRNA in mammary tumor samples is a possible mechanism to explain mammary tumor development in dogs." (PMID 26202431, 2015). "Inherited germ-line mutations in the high risk genes BRCA1, BRCA2, and PALB2 are identified in approximately 20 percent of these breast cancer families." (PMID 26553136, 2015). "For example breast cancer susceptibility mutation BRCA contains two genes; in CGMD, BRCA is included as cancer mutation and each of characterized genes BRCA1 and BRCA2 are considered as two independent genes." (PMID 26160459, 2015). "Represented by the rs80358972 SNP, the p.Arg2494Stop affecting BRCA2 has been reported by the Breast Cancer Information Core submitted by Myriad Genetics as a direct result of their diagnostic services." (PMID 25923920, 2015). "In BRCA2-deficient cells, including certain types of breast cancer, RAD52 substitutes for the missing BRCA2 by recruiting RAD51 to the site of DNA breaks, suggesting that BRCA2 and RAD52 play very similar roles in the HDR pathway." (PMID 25809609, 2015). "In this case-control study of women from high-risk breast cancer families, we confirmed that breast density was an independent risk factor for BC among BRCA1 and BRCA2 mutation carriers." (PMID 26163143, 2015).
breast cancer (continued). "Our results suggested that low BRCA2 expression in canine mammary tumors is a possible mechanism that leads to tumorigenesis." (PMID 26202431, 2015). "Approximately 5% to 10% of breast cancer cases and 11% to 18% of ovarian cancer cases are a result of a mutation in the BRCA1 and BRCA2 genes, known as hereditary breast and ovarian cancer (HBOC)." (PMID 26557407, 2015). "According to the Breast Cancer Information Core (BIC), more than 1800 and 2000 distinct variants of the BRCA1 and BRCA2 genes have been described, respectively." (PMID 25948282, 2015). "Retrospective analyses have indicated that bilateral risk reduction mastectomy (BRRM) decreases breast cancer risk by at least 90 % in BRCA1 and BRCA2 mutation carries." (PMID 26669313, 2015). "Another possible weakness of our study is the usage of external estimates of breast cancer and OvC relative risks to BRCA1 and BRCA2 mutation carriers." (PMID 26025000, 2015). "In this study, we compared the expression levels of canine BRCA2 in mammary gland tissue and mammary tumor samples." (PMID 26202431, 2015). "Recently, additional common alleles have been reported to be associated with increased breast cancer risk for BRCA1 and BRCA2 mutation carriers in large retrospective studies." (PMID 25339628, 2015). "To determine the prevalence and clinical significance of PARP1, BRCA1 and BRCA2 in breast cancer development, we investigated their expression in 110 cases of tissues and adjacent normal tissues by using immunohistochemistry." (PMID 25865228, 2015). "(2006) observed a 50% reduction in contralateral breast cancer in carriers of both BRCA1 and BRCA2 mutations when tamoxifen was given as treatment for the initial breast cancer diagnosis." (PMID 26557407, 2015). "Further studies are needed to reveal the correlation between canine BRCA2 transcript and protein levels in mammary tumor samples." (PMID 26202431, 2015). "The expression of both PARP1 and BRCA1, both PARP1 and BRCA2, or both BRCA1 and BRCA2 in breast cancer were 17%, 22%, and 15%, respectively." (PMID 25865228, 2015). "For example, the synthetic lethal interaction between BRCA2 mutations and PARP inhibition in breast cancer cells has led to the clinical use of PARP inhibitors in breast cancer patients." (PMID 26227665, 2015). "Though the focus of our review was to determine the association between breast cancer prognosis and carriership of the BRCA1 and BRCA2 mutations separately, there were many studies combining both groups in their analyses." (PMID 25816289, 2015). "First, the status of the known breast cancer predisposition factors, mainly BRCA1 and BRCA2, was determined." (PMID 25923920, 2015). "The expression level of canine BRCA2 in mammary tumor samples was lower than levels in mammary gland samples." (PMID 26202431, 2015). "This conferred an approximate 95% reduction in breast cancer risk in BRCA1- and BRCA2-mutation carriers." (PMID 26557407, 2015). "The data involve variants in the coding and flanking intron sequences of the human BRCA1 and BRCA2 genes in Hispanic subjects with breast cancer." (PMID 26543556, 2015).
breast cancer (continued). "Breast carcinomas showed extensive miRNA alteration compared to normal breast tissues in BRCA1 and BRCA2 mutation carriers." (PMID 26378051, 2015). "miR-99a was down-regulated in breast carcinomas compared to normal breast tissues in both BRCA1 and BRCA2 germ-line mutation carriers." (PMID 26378051, 2015). "Up to 5–10 % of all BC cases and 10–15 % of all ovarian cancer (OC) cases are due to germline mutations in one of the two breast cancer susceptibility genes, BRCA1 [MIM#113705] and BRCA2 [MIM#600185]." (PMID 26183948, 2015). "We extracted seven genes, XRCC3, XRCC2, RAD51C, RAD51L1, RAD51L3, FANCG, BRCA2, that formed a connected PPI network with eight interactions, and had been associated with breast cancer as well as other types." (PMID 24784581, 2014). "A total of 244 breast cancer patients were tested for BRCA1 and BRCA2 mutations using a combination of laboratory techniques." (PMID 24742220, 2014). "We also analyzed the associations of about 200,000 variants on the iCOGS genotyping array with subtype-specific breast cancer risk in carriers in an attempt to uncover previously unreported subtype-specific associations in women with BRCA1 and BRCA2 mutations." (PMID 25919761, 2014). "The complexes in breast tumours reflected aberration in Homologous recombination (HR), a key DSB-repair pathway which includes the breast cancer susceptibility genes BRCA1 and BRCA2." (PMID 25521701, 2014). "Similar to mutations in BRCA1 and BRCA2, the risks associated with monoallelic mutations in PALB2 seem to extend beyond breast cancer." (PMID 25225577, 2014). "While little is known about the DDR in canine mammary cancer, comparable BRCA2 and Rad51 misregulations, point towards a high possibility of similarly altered HR pathway in the two species." (PMID 24641873, 2014). "Hereditary genetic factors are thought to account for approximately 5 to 10% of breast cancers due to germ-line variants in genes that increase the risk for breast cancer, such as BRCA1 and BRCA2." (PMID 25036186, 2014). "This is reminiscent of Rpn11 and BRCC36 (for BRCA1 (for Breast Cancer 1)/BRCA2 (for Breast Cancer 2)-Containing Complex subunit 36) found in the 26S proteasome lid and BRCC36-containing complexes, respectively, that are also inactive in the stand-alone form." (PMID 25144743, 2014). "We compared the log HR estimates for the breast cancer association of known breast cancer susceptibility variants for BRCA1 carriers, BRCA2 carriers, and for the general population using published data from the Breast Cancer Association Consortium (BCAC)." (PMID 25919761, 2014). "FOXM1 regulates XRCC1 and BRCA2 in HER positive breast cancer, in triple-negative breast cancer, however, FOXM1 transactivates EXO1 and PLK4 in response to doxorubicin." (PMID 24824601, 2014). "Similar to BRCA2, germline mutations in PALB2 have been shown to predispose to Fanconi anaemia as well as pancreatic and breast cancer." (PMID 24949998, 2014). "The first clinical evidence for the importance of FANCJ was the identification of germ line sequence changes in FANCJ that were associated with early breast cancer in two individuals that displayed normal genotypes for BRCA1 and BRCA2." (PMID 25374583, 2014). "For example, breast cancer cells with mutations in the BRCA1 and BRCA2 are sensitive to inhibition of poly [ADP-ribose] polymerase (PARP1), whereas inhibition of PARP1 has little influence on survival and proliferation of normal cells with WT BRCA." (PMID 24150935, 2014). "FA represents a unique model disorder that raised general attention in the last decade since it was discovered that one of the encoded proteins by the FA subgroup D1 (FANCD1) was identical with the breast cancer-related BRCA2 gene." (PMID 25594021, 2014).
breast cancer (continued). "HBOC syndrome accounts for 5–7% of all cases of breast cancer, and patients carrying the mutation have a lifetime risk for developing breast cancer of 50–80% and 30–50% for ovarian cancer (both BRCA1 and BRCA2)." (PMID 24959366, 2014). "The breast cancer susceptibility proteins, BRCA1 and BRCA2, have a key role in efficient HR response to DSBs." (PMID 24795863, 2014). "Under such a model, the effects of common breast cancer susceptibility variants and of BRCA1 and BRCA2 mutations on breast cancer risk would be multiplicative, after taking into account tumor ER status." (PMID 25919761, 2014). "This is the first comprehensive report, to our knowledge, of the associations of genetic variants with risk of developing breast cancer by tumor subtypes in BRCA1 and BRCA2 carriers." (PMID 25919761, 2014). "b) modified transmission of BRCA2 gene competes in the occurrence of the breast cancer and especially in ovarian cancer." (PMID 25870675, 2014). "The tumor suppressor genes BRCA1 and BRCA2 (Breast Cancer 1 and 2, early-onset) are involved in DNA repair mechanisms and are often mutated in breast cancer." (PMID 25322458, 2014). "The two major contributors to hereditary breast cancer are the breast cancer susceptibility gene 1 (BRCA1) and BRCA2." (PMID 24961674, 2014). "In the present study, we assessed the disease subtype-specific associations of all 74 previously reported breast cancer susceptibility variants in 15,252 BRCA1 and 8,211 BRCA2 carriers." (PMID 25919761, 2014). "Mutations at or deregulation of certain genes (BRCA1, BRCA2, HER2, PIK3CA) and others play important roles in breast cancer." (PMID 25051360, 2014). "From this cohort, three at risk individuals and two familial breast cancer patients were positive for clearly pathogenic BRCA1 mutations and only six familial breast cancer patients were positive for clearly pathogenic BRCA2 mutations." (PMID 24906410, 2014). "It has been also reported in the context of a positive family history of breast cancer and among BRCA1 and BRCA2 mutation carriers." (PMID 25277819, 2014). "Genetic screening for mutations in the breast cancer susceptibility genes BRCA1 and BRCA2 for families at high risk is a well established diagnostic modality." (PMID 24695549, 2014). "In Canada and other countries, women with significant family history of breast and/or ovarian cancer are eligible for genetic testing for mutations in either one of the two breast cancer susceptibility genes, BRCA1 and BRCA2 (BRCA1/2)." (PMID 24667084, 2014). "By age 70, approximately 60–70% and 45–55% of BRCA1 and BRCA2 mutation carriers will develop breast cancer, respectively; 40% and 20% of BRCA1 and BRCA2 mutation carriers will develop ovarian cancer." (PMID 24586286, 2014). "For example, PLD3 is identified as one of irradiation-responsive genes in human lymphoblastoid cells, serving as a genetic modifier for breast cancer susceptibility genes BRCA1 and BRCA2, suggesting a role of PLD3 in DNA damage response." (PMID 25478031, 2014).
breast cancer (continued). "The dataset included 4,477 BRCA1 mutation carriers, 2,565 BRCA2 mutation carriers, and 47,565 BCAC breast cancer cases." (PMID 25857409, 2014). "In fact, Poly-ADP-ribose polymerase 1 (PARP1), which plays a signaling role in the DNA Base Excision Repair pathway (BER), is critical for viability of familial breast cancer cells deficient in HR proteins BRCA1 and BRCA2." (PMID 25185513, 2014). "BRCA1 and BRCA2 were predominantly methylated in breast cancer while p14 was more frequently methylated in oesophageal and colon cancer samples, ranging in frequency between 33.3% and 70%." (PMID 24607238, 2014). "Defects in the BRCA1 or BRCA2 genes are responsible for most hereditary forms of breast cancer and account for as many as 10% of all breast cancer cases." (PMID 25011685, 2014). "A recent study has shown that variations in the BRCA1 and BRCA2 genes are associated with CMT in ESSs and these genes are responsible for early onset of breast cancer in women." (PMID 25293656, 2014). "For BRCA2 carriers, SNPs at loci 10q26 (FGFR2) and 16q12.1 (TOX3) were associated with all subtypes of breast cancer." (PMID 25919761, 2014). "RAD51 (RAD50 forms MRE11-NSB1-RAD50 complex) also interacts with breast cancer susceptibility genes 1 and 2 (BRCA1/BRCA2)." (PMID 24752797, 2014). "We show that mutations are more likely to be found in families with three or more breast cancers as well as other BRCA2-related cancers." (PMID 25225577, 2014). "Genetic variants of both BRCA2 and the DNA repair gene MRE11A have been associated with the development of breast cancer in Cyprus." (PMID 24678344, 2014). "To date, most individuals with a strong family history of breast cancer are only tested for BRCA1 and BRCA2 variants due to well established preventative treatment and surveillance guidelines." (PMID 24830819, 2014). "Currently, oral intake of PARP inhibitors has shown a favorable therapeutic score for breast cancer with acceptably low toxicity in women with the BRCA1 and BRCA2 mutation." (PMID 24317580, 2014). "Two major breast cancer susceptibility genes are BRCA1 and BRCA2, located on chromosomes 17 and 13, respectively and both perform function as tumor suppressor genes." (PMID 24711893, 2014). "Most notable are the discoveries of the BRCA1 and BRCA2 genes, identified in multiple-case family studies in which breast cancer cases were observed to follow a Mendelian pattern of inheritance." (PMID 25112280, 2014). "The two major high-penetrance breast cancer susceptibility genes, BRCA1 and BRCA2, account for approximately 26% of all cases of hereditary breast and/or ovarian cancer (HBOC)." (PMID 24686251, 2014). "A particular set of tumour suppressors associated with breast cancer is the Breast Cancer 1 and 2 gene set (BRCA1 and BRCA2)." (PMID 25548681, 2014). "Mutations in the BRCA genes are responsible for the increased risk of breast cancer, specifically 59–87 and 38–80% for BRCA1 and BRCA2 mutations respectively." (PMID 24795863, 2014).